WNT5A (Wnt family member 5A)
Diseases named in the same sentence as WNT5A in open-access papers (continued):
Sharing a sentence is not in itself a finding about the gene and the disease.
lung fibrosis (continued). "Zhang and colleagues showed that MSC-Exos increased Wnt5a/BMP2-driven signaling and suppressed Wnt/β-catenin-dependent collagen deposition and EMT in inflamed and fibrotic lungs, which resulted in the attenuation of pulmonary fibrosis." (PMID 38673961, 2024). "Both WNT5A and IL11 related canonical pathways were selected and two canonical pathways were found in common between the four transduced cell lines: Cardiac Hypertrophy Signaling and Pulmonary Fibrosis Idiopathic Signaling." (PMID 37545510, 2023). "(D) RNA-seq analysis shows upregulation of WNT5A and WNT11, non-canonical WNTs associated with pulmonary fibrosis (* p<0.05, ** p<0.01, *** p<0.001, **** p<0.0001, DEseq2 pairwise contrast statistics)." (PMID 35559731, 2022). "WNT5a is a mainly “non-canonical” WNT ligand whose dysregulation is observed in lung diseases such as idiopathic pulmonary fibrosis (IPF), chronic obstructive pulmonary disease (COPD) and asthma." (PMID 32046118, 2020). "WNT5a, a non-canonical Wnt ligand, is highly induced in lung fibrosis." (PMID 34445242, 2021). "Although it was shown that SMC from asthmatic patients can also be a source of Wnt5a, currently there are no reports that have analyzed the role of SMC derived Wnt5a in the development of lung fibrosis." (PMID 34451852, 2021). "WNT5A was identified as a predominant noncanonical WNT ligand in fibrotic diseases such as systemic sclerosis, sclerodermatous chronic graft-versus-host disease, and idiopathic pulmonary fibrosis, stimulating fibroblast-to-myofibroblast transition and tissue fibrosis by activation of latent TGF-β." (PMID 38747285, 2024).
Robinow syndrome (24 papers, 2011 to 2026). Robinow syndrome (RS) is a rare genetic syndrome characterized by limb shortening and abnormalities of the head, face and external genitalia. "Mutations of WNT5A have been associated with Robinow syndrome, a congenital condition characterized by skeletal and genital anomalies." (PMID 41744802, 2026). "Craniofacial and dental phenotype differed between mice with conditional GOF and LOF of Wnt5a, consistent with the craniofacial phenotype heterogeneity in Wnt5a-associated Robinow syndrome." (PMID 40777421, 2025). "Mutations in WNT5A are one cause of Robinow syndrome, and Wnt5a mutant mice have dysmorphic pituitary glands with early alterations in BMP and FGF signaling." (PMID 39975280, 2025). "Among the genetic causes associated with these phenotypes, pathogenic variants in DVL1/DVL3 and WNT5A (all (i.a.)for Robinow syndrome) and TCTN3 (orofaciodigital syndrome 4) have been identified." (PMID 34629465, 2022). "In humans, heterozygous missense or homozygous truncating variants in WNT5A are associated with multisystem ‘Robinow syndrome’ (OMIM: 180700), with right ventricular outlet obstruction occurring as a relatively rare associated anomaly." (PMID 33110418, 2020). "Although potentially interacting pathways were not clear in the chick model, the implication of YAP/TAZ and PIEZO1 downstream of WNT5A suggests that multiple processes are likely affected by mutations that cause Robinow syndrome." (PMID 30979871, 2019). "A dominant form of RS is caused by mutations in Wnt/PCP components DVL1, DVL3, and WNT-5A, it is therefore believed that the developmental defects seen in Robinow syndrome are caused by a deregulation of Wnt-5a/Ror2/PCP signaling." (PMID 28523267, 2017). "Skeletal dysplasia due to Smad4 deficiency resembles other skeletal dysplasias resulting from mutations in polarity pathways, such as the Ror2/Wnt5a PCP pathway with Robinow syndrome and brachydactyly B2." (PMID 28167493, 2017). "Our studies implicate Prickle1 as a key component of the Wnt-signaling pathway and suggest that Prickle1 mediates some of the WNT5A-associated genetic defects in Robinow syndrome." (PMID 25190059, 2014). "Curiously, Prickle1 mutants recapitulate the characteristic features of human Robinow syndrome and phenocopy mouse mutants with Wnt5a or Ror2 gene defects, prompting us to explore an association of Prickle1 with the Wnt pathway." (PMID 25190059, 2014). "Cystic kidney has also been observed in Robinow syndrome patients with mutations in Ror2, a receptor for Wnt5a." (PMID 25190059, 2014). "In conclusion, the craniofacial and dental phenotype differed between mice with conditional GOF and LOF of Wnt5a in Ctskcre-expressing cells, consistent with other preclinical reports and the craniofacial phenotype heterogeneity in Wnt5a-associated Robinow syndrome." (PMID 40777421, 2025). "Consequently, mandibular manifestations of WNT5A mutations are variant consequence-dependent consistent with micrognathia occurring in only 33–57% of individuals with Robinow syndrome." (PMID 40777421, 2025). "The mutations of APC may cause Gardner syndrome, besides gene mutations of Ror2, Dvl1, Dvl3 and Wnt5a are associated with Robinow syndrome." (PMID 37194731, 2023). "In addition to the bulldog DVL2 frameshift mutation, human mutations causing Robinow syndrome have been identified in WNT5A, ROR2, FZD2, DVL1, and DVL3, which are all major components of the WNT5A-ROR pathway." (PMID 30521570, 2018). "Furthermore, mutations in either Wnt5a or its receptor Ror2 in humans lead to Robinow syndrome, distinct from that of other PCP gene mutations." (PMID 25190059, 2014). "Indeed, Ror2−/− and Wnt5a−/- mouse embryos exhibit dwarfism, short limbs and tail, facial anomalies, and ventricular septal defect, reminiscent of features observed in patients with Robinow syndrome that is caused by loss-of-function mutations in Ror2 or Wnt5a genes." (PMID 35493090, 2022).
Robinow syndrome (continued). "One key finding of this study was that conditional LOF and conditional GOF of Wnt5a result in distinct craniofacial phenotypes reminiscent of the heterogeneity of craniofacial phenotypes in individuals with Robinow syndrome." (PMID 40777421, 2025). "Outside of the Robinow syndrome patient population, this study demonstrates the important craniofacial and dental role of Wnt5a." (PMID 40777421, 2025). "The craniofacial and dental manifestation of Robinow syndrome is heterogenous, as is the effect of altered Wnt5a in animal models." (PMID 40777421, 2025). "Variants in DVL, together with variants in WNT5a and ROR2, have been associated with Robinow syndrome, a condition associated with skeletal malformations." (PMID 40271154, 2025). "Robinow syndrome can also be caused by mutations in other genes that are important in the WNT/PCP signaling pathway, including WNT5A, the disheveled genes DVL1, DVL2, and DVL3, and the WNT co-receptors FZD2 and ROR28,9." (PMID 39975280, 2025). "(B) Quantification of the effects of Robinow syndrome ROR2 mutants in rescuing WNT5A-ROR signaling, as assayed by GFP-Pdzrn3 degradation." (PMID 38780011, 2024). "Mutations in genes from WNT pathways, including ROR2, FZD2, WNT5A, DVL1, and DVL3, have all been found to cause Robinow syndrome in humans." (PMID 30521570, 2018). "The phenotypic similarity and its role in mediating Wnt5a/Ror2 signaling make Prickle1 a likely candidate gene for Robinow syndrome." (PMID 25190059, 2014). "Wnt5a signaling is essential for normal developmental morphogenesis resulting in abnormal craniofacial and skeletal development in Wnt5a null mice, and Robinow Syndrome in humans." (PMID 21738662, 2011). "Our results indicate additional roles for Wnt5a during Müllerian duct development, prompting further investigations into uterine functions and anatomy in complex clinical cases of Müllerian anomalies including Robinow syndrome." (PMID 41744802, 2026). "We detected tooth eruption delay, mandibular condyle dysmorphology, and facial asymmetry in mice with altered Wnt5a that have not been previously reported in patients with WNT5A-associated Robinow syndrome." (PMID 42110975, 2026). "Robinow syndrome has characteristic craniofacial and dental features and can be caused by gain- or loss-of-function variants in Wnt family member 5A (WNT5A) non-canonical signaling." (PMID 40777421, 2025). "Robinow syndrome occurs due to pathogenic variants in Wnt family member 5A (WNT5A) or other members of the WNT5A non-canonical signaling pathway." (PMID 40777421, 2025). "Robinow syndrome can also be caused by mutations in other genes that are important in the WNT/PCP signaling pathway, including WNT5A (OMIM 180700), the disheveled genes DVL1 (OMIM 616331), DVL2, and DVL3 (OMIM 616894), and the WNT co-receptors FZD2 and ROR2 (OMIM 268310)." (PMID 40044116, 2025). "Lastly, Wnt5a may play a bone-specific role as demonstrated by differences in mandibles and femurs of conditional Wnt5a knockout and in patients with Robinow Syndrome." (PMID 40777421, 2025). "Recent evidence suggests that perturbations in WNT5A non-canonical signaling from loss-of-function, gain-of-function, or hypomorphic variants in WNT5A can all result in Robinow syndrome." (PMID 40777421, 2025). "Temporomandibular joint disorders in individuals with Robinow syndrome are not reported in the literature, though there is an association between Wnt5a signaling and TMJ dysfunction in other animal models." (PMID 40777421, 2025). "The receptor tyrosine kinase ROR2 mediates noncanonical WNT5A signaling to orchestrate tissue morphogenetic processes, and dysfunction of the pathway causes Robinow syndrome, brachydactyly B, and metastatic diseases." (PMID 38780011, 2024).
Robinow syndrome (continued). "Seven children with Robinow syndrome were enrolled in this study (autosomal recessive caused by homozygous mutations in the ROR2 gene on chromosome 9q22, and the autosomal dominant caused by heterozygous mutation in the WNT5A gene on chromosome 3p14)." (PMID 32172608, 2020). "Furthermore, Prickle1 has been shown to act downstream of Wnt5a and interact with Dvl2, and Prickle1 mutants display characteristics that resemble Robinow syndrome." (PMID 30760477, 2019). "Craniofacial asymmetries have not been reported in individuals with WNT5A-associated Robinow syndrome, but clinical photographs of individuals with Robinow syndrome suggest asymmetries may be present but not documented." (PMID 40777421, 2025). "This may explain why some individuals with WNT5A-associated Robinow syndrome have mild osteopenia of the non-cranial skeleton but normal BMD in the cranial skeleton." (PMID 40777421, 2025). "Interestingly, autosomal dominantly inherited WNT5A dysfunction also results in right-ventricular outflow tract obstruction and renal anomalies with incomplete penetrance in addition to skeletal dysplasia features [Robinow syndrome; Online Mendelian Inheritance in Man (OMIM) #180700)]." (PMID 40200693, 2025). "Further, we detected tooth eruption delay, TMJ changes, and facial asymmetry in mice with altered Wnt5a that have not been previously reported but for which patients with Robinow syndrome should be monitored." (PMID 40777421, 2025). "One of these, Robinow syndrome, is caused by mutations in components of the noncanonical WNT pathway including WNT5A (autosomal-dominant form) and ROR2 (recessive form) which encode a ligand and a downstream receptor tyrosine kinase, respectively." (PMID 30979871, 2019).
asthma (23 papers, 2013 to 2024). "The variant rs67026078, located within the intergenic region between CACNA2D3 and WNT5A, was associated with asthma exacerbations in children." (PMID 33923891, 2021). "The interaction between TGF-β1 and Wnt-5a is associated with various pathophysiological functions in asthma." (PMID 27297409, 2016). "Interestingly, there was an increase in WNT-5A, which is highly associated with asthma with high Th2 levels, suggesting a possible role of the non-canonical pathway in this case." (PMID 39337534, 2024). "Interestingly, it was discovered in a genome-wide association study that Wnt5A is a novel locus for asthma exacerbations despite treatment with inhaled corticosteroids in European but not in non-European populations." (PMID 36658268, 2023). "The produced Wnt5A may affect locally immune cells, for instance mast cells, which are associated with asthma and other allergic diseases." (PMID 36658268, 2023). "Notably, WNT5A expression in bronchial biopsies is linked to Th2-high asthma." (PMID 36550577, 2022). "The same results were obtained after inducing IL-4, proving that Wnt5a was overexpressed in HBECs during asthma." (PMID 38898476, 2024). "Using GEO datasets and in vitro cultured HBECs, we uncovered that WNT5A (Wnt5a) is highly enriched in the HBECs from asthma patients, lung of asthma mice, and HDM or IL-4-treated HBECs." (PMID 38898476, 2024). "In this study, for the first time, we demonstrate that Wnt5a is a novel modulator of EMT in HBECs during asthma." (PMID 38898476, 2024). "DNA microarray research has shown that patients with asthma have higher levels of Wnt5a expression in their peripheral blood, which is strongly associated with the disease." (PMID 38898476, 2024). "Asthma patients exhibited a significant increase in the gene expression of WNT5A compared to the healthy control." (PMID 38898476, 2024). "Wnt5a has been implicated in various lung diseases, while its role in the EMT of HBECs during asthma is yet to be determined." (PMID 38898476, 2024). "In this review, we summarize the literature available regarding the role of Wnt5A as an immune modulator and its role in the development of asthma, COPD and IPF." (PMID 36658268, 2023). "Beside immune cells, structural cells are involved in asthma and some of them are known to release Wnt5A." (PMID 36658268, 2023). "Overall, there are less data for the involvement of Wnt5A in disease progression for COPD than for asthma." (PMID 36658268, 2023). "These possibilities of a detailed elucidation of Wnt5A can offer new starting points for Wnt-based therapeutic approaches for lung diseases such as asthma, COPD, or IPF in the future." (PMID 36658268, 2023). "JNK also plays a meaningful role in the airway remodeling and apoptotic process by inducing the Wnt5a/JNK signaling pathway in asthma." (PMID 35743888, 2022). "The ROC curves illustrated that FKBP5, WNT5A, PDK4, and GMPR had potential diagnostic value for asthma." (PMID 36550577, 2022). "PDK4 (P-value < 0.001) and ZBTB16 (P-value < 0.01) were up-regulated in asthma group, while WNT5A (P-value < 0.05), NR4A3 (P-value < 0.001) and WIF1 (P-value < 0.05) were down-regulated." (PMID 36550577, 2022). "Among them, PDK4, FKBP5, ZBTB16, WNT5A, GMPR and WIF1 are reported to be associated with asthma in the previous researches." (PMID 36550577, 2022). "Our results show a role for WNT5A in T helper 2 (Th2)-cell immunity, which is a novel finding relevant to asthma pathophysiology." (PMID 32317758, 2020). "Future efforts should entail more mechanistic studies to characterize the relationship between WNT5A and Th2 driven inflammation in asthma." (PMID 32317758, 2020). "Our findings imply a pro-inflammatory role for smooth muscle-derived WNT5A in asthma, resulting in increased airway wall inflammation and remodelling." (PMID 32317758, 2020).
asthma (continued). "JNK, a stress-activated protein kinase and a member of the mitogen-activated protein kinase (MAPK) family, has significant roles in the apoptotic process and airway remodeling in asthma by inducing the Wnt5a/JNK signaling pathway." (PMID 31637021, 2019). "To investigate the effect of eosinophils from asthma patients on Wnt-5a and TGF-β1 gene expression, we determined the total mRNA levels of these genes in ASMC after incubation with eosinophils." (PMID 27297409, 2016). "This supposition is supported by findings that Wnt-5a expression is increased in ASMC from asthma patients and that Wnt-5a gene expression is enriched in biopsies from patients with Th2-high asthma." (PMID 27297409, 2016). "In summary, eosinophils from patients with asthma increase Wnt-5a and TGF-β1 gene expression in ASMC, enhance the expression of collagen and fibronectin, and promote ASMC proliferation." (PMID 27297409, 2016). "Herein, we hypothesized that elevated Wnt5a expression in asthma could activate excessive autophagy through the Ca2+/CaMKII pathway, leading to the induction of the EMT process and airway remodeling, ultimately exacerbating asthma." (PMID 38898476, 2024). "Consistently, Wnt5a levels were elevated in the lung of asthma mice, compared to controls." (PMID 38898476, 2024). "Microarray analysis was used to investigate the expression change of WNT5A in asthma patients." (PMID 38898476, 2024). "Asthma medication that targets Wnt5a may be effective, opening up new possibilities for the diagnosis and management of this condition." (PMID 38898476, 2024). "Together, both in vivo and in vitro results consistently indicate that the expression of WNT5A is enriched during asthma, and WNT5A may be strongly correlated with EMT." (PMID 38898476, 2024). "Impressively, we found that WNT5A was highly enriched in HBECs from patients with asthma." (PMID 38898476, 2024). "Furthermore, analysis of transcriptome data from asthma patients’ HBECs revealed elevated Wnt5a gene expression." (PMID 38898476, 2024). "The study suggests that Wnt5a-mediated activation of the Ca2+/CaMKII axis could be a novel target for the treatment of EMT during asthma." (PMID 38898476, 2024). "Many of these observations point to a role of Wnt5A as a bad guy in asthma." (PMID 36658268, 2023). "Altogether these results imply that the role of Wnt5A in asthma may depend on the timing of its release." (PMID 36658268, 2023). "FKBP5, WNT5A, TM4SF1, PDK4, EPAS1 and GMPR had potential diagnostic value for asthma." (PMID 36550577, 2022). "The AUC value of FKBP5 (AUC = 0.832), WNT5A (AUC = 0.813), TM4SF1 (AUC = 0.769), PDK4 (AUC = 0.753), EPAS1 (AUC = 0.748) and GMPR (AUC = 0.705) was more than 0.7, which suggesting higher diagnostic value for asthma." (PMID 36550577, 2022). "To directly follow up from these results, we additionally treated CD4+ T cells of asthma patients and healthy controls with WNT5A, and used bulk RNA-seq to reveal transcriptional changes and identify WNT5A induced cytokines that could mediate this." (PMID 32317758, 2020). "Overall then, ASM-derived WNT5A is likely to be relevant in the context of asthma." (PMID 32317758, 2020). "In addition, CD4+ T cells of asthma patients and healthy controls were stimulated with WNT5A and changes in gene transcription assessed by RNA-seq." (PMID 32317758, 2020). "Here, we aimed to characterize the functional role of (smooth muscle-derived) WNT5A in asthma." (PMID 32317758, 2020). "Furthermore, vitamin D reduces the expression of Wnt5a and β-catenin and effectively inhibits the activity of the Wnt/β-catenin signaling pathway, preventing airway remodeling in asthma." (PMID 31637021, 2019). "WNT-5A is increasingly expressed in asthmatic ASM and has been linked with Th2-high asthma." (PMID 27468699, 2016).